STAT3 (signal transducer and activator of transcription 3)
Diseases named in the same sentence as STAT3 in open-access papers (continued):
Sharing a sentence is not in itself a finding about the gene and the disease.
bladder cancer (continued). "At the same time, we detected STAT3 and p-STAT3 in bladder cancer and para-cancerous normal tissues by IHC assay." (PMID 36227136, 2022). "Given that HME suppresses STAT3 activation, we aimed to define the role of STAT3 inhibition in HME-mediated bladder cancer cell death." (PMID 36613579, 2022). "Collectively, these data supported that HME blocks STAT3 activation by suppressing SRC activity in bladder cancer cells." (PMID 36613579, 2022). "Knock-down of PYCR1 inhibited the viability, proliferation, invasion and EMT of bladder cancer cells that were induced by STAT3." (PMID 36227136, 2022). "AKT/STAT3-mediated M2 polarization was also induced by tumor-derived miR-92b-3p and miR-1231-5p in bladder cancer." (PMID 36248881, 2022). "After establishing a pivotal role of STAT3 blockage in HME’s cytotoxic action, we further explored the candidate effectors downstream of STAT3 to mediate HME-induced bladder cancer cytotoxicity." (PMID 36613579, 2022). "Mounting evidence has substantiated the notion that blockage of STAT3 activation is a promising therapeutic strategy for multiple human malignancies, including bladder cancer." (PMID 36613579, 2022). "Accordingly, these findings illustrate that blockade of STAT3 activation is required for HME-elicited cytotoxicity in bladder cancer cells." (PMID 36613579, 2022). "STAT3 was not only found to be upregulated in 10 types of bladder cancer cell lines but also in invasive bladder cancer tissue samples." (PMID 36230984, 2022). "This cytotoxic action is attributed to the induction of bladder cancer cell apoptosis by thwarting the antiapoptotic SRC/STAT3/survivin signaling axis." (PMID 36613579, 2022). "Cancer-associated fibroblasts secreted IL-6, which activated its receptor on bladder cancer cells, subsequently leading to the increased phosphorylation of STAT3 and providing IL-6-activated EMT programming." (PMID 36230984, 2022). "Next, we found that knockdown of PYCR1 inhibited Epithelial to mesenchymal transition of bladder cancer, and simultaneously mitigated the carcinogenic effects of STAT3." (PMID 36227136, 2022). "We sought to clarify how SENP3 affects PYCR1 and STAT3 to regulate the development of bladder cancer." (PMID 36227136, 2022). "In conclusion, we first report HME’s cytotoxic effect on human bladder cancer cells via suppression of the antiapoptotic SRC/STAT3/survivin signaling axis." (PMID 36613579, 2022). "Recent evidence further underpins the STAT3 signaling pathway as a central mechanism whereby oncogenes promote bladder cancer progression." (PMID 36613579, 2022). "In all, results lend novel insights into the regulation of STAT3, which has key roles in bladder cancer progression." (PMID 36227136, 2022). "Supporting our findings, STAT3 was also reported to promote cell proliferation in bladder cancer cell lines, WH, UMUC-3, and 253 J." (PMID 35659036, 2022). "It is also noteworthy that pharmacological inhibition of STAT3 has been demonstrated to effectively suppress bladder cancer cell progression in vitro and in vivo, thus validating STAT3 blockage as a potential strategy for bladder cancer therapy." (PMID 36613579, 2022). "Altogether, the evidence supports that HME represses the SRC/STAT3/survivin signaling axis to inhibit cell viability and clonogenicity of bladder cancer cells, consequently exerting cytotoxicity." (PMID 36613579, 2022). "STAT3 has been shown to affect cellular metabolism, through increased glucose consumption, and lactate production in bladder cancer, through increased transcription of LDHA, ENO2, HK2, and IGFBP3." (PMID 36230984, 2022). "This study found that SENP3 induced deSUMOylation of STAT3 remarkably promote bladder cancer proliferation and EMT." (PMID 36227136, 2022). "The aim of the present study was to explore the effect and mechanism of STAT3 and its activation in bladder cancer." (PMID 36227136, 2022).
bladder cancer (continued). "In bladder cancer, persistent STAT3 activation is proven to sustain cell proliferation and survival, facilitate metastasis, and promote chemoresistance." (PMID 36613579, 2022). "In bladder cancer cells, metformin improves the antitumor effect of Olaparib through the STAT3/C-MYC pathway." (PMID 36385965, 2022). "Accumulating evidence has underscored the link between aberrant STAT3 activation and the malignant progression of diverse human cancers, including bladder cancer." (PMID 36613579, 2022). "The GEPIA database of bladder cancer showed that STAT3 expression in bladder cancer tissues was lower than that in adjacent normal tissues." (PMID 36227136, 2022). "GLN not only regulates STAT3 by glutaminolysis and ATP supplementation but also through ROS level modulation in bladder cancer cell lines." (PMID 36230984, 2022). "While BLCAP has been reported to be a tumor suppressor gene promoting apoptosis, its product interacts with STAT3 and has been suggested to promote bladder cancer progression." (PMID 36461044, 2022). "The initiation and progression of bladder cancer are mediated by alterations in multiple signaling cascades, such as Akt (protein kinase B), STAT3 (signal transducer and activator of transcription), and NF-κB (nuclear factor-kappa B)." (PMID 34332611, 2021). "We found that GSDMB bound to and activated STAT3 to modulate the glucose metabolism and promote tumor growth in bladder cancer cells." (PMID 34326684, 2021). "Here, our results indicated that USP24 bound to GSDMB to stabilize GSDMB, and subsequently activated the STAT3 pathway in bladder cancer cells." (PMID 34326684, 2021). "The Janus kinases (JAK)/signal transducer and activator of transcription 3 (STAT3) axis is abnormally activated in bladder cancer and correlated with the poor prognosis 4-6." (PMID 34326684, 2021). "For more understanding of the molecular mechanisms downstream of lnc-STYK1-2 and miR-146b-5p, we analyzed the influence of lnc-STYK1-2 and its suppression of miR-146b-5p on the expression of ITGA2 and AKT/NFκB/STAT3 axis activation in bladder cancer cells." (PMID 34332611, 2021). "It promotes cell proliferation and metastasis through regulation of STAT3 phosphorylation in bladder cancer cells." (PMID 34239347, 2021). "For instance, reactive oxygen species and glutaminolysis are reported to activate STAT3 in bladder cancer." (PMID 34326684, 2021). "In the present study, we identified that MB49-derived exosomes contribute to immunosuppressive phenotype and function of TAM polarization by activating PTEN/AKT/STAT3 signaling pathways, thus promoting bladder cancer growth." (PMID 34521440, 2021). "It has been observed that expression level of STAT3 correlates with invasion and poor prognosis in bladder cancer." (PMID 32046095, 2020). "We observed that with these inhibitors proliferation in bladder cancer was greatly reduced which is in line with previous studies on STAT3 inhibition." (PMID 32046095, 2020). "Mao et al38 discovered that miR‐181a‐5p interacts with fibroblast growth factor receptor 3 (FGFR3) to promote the progression of bladder cancer through the activation of the STAT3 pathway." (PMID 33002329, 2020). "In conclusion, we show that targeting of STAT3 along with chemotherapy or CDK4/6 inhibitors provide potential combination therapy options in order to improve therapy efficacy in bladder cancer." (PMID 32046095, 2020). "The present study was aimed to explore the expression of CDk4 and STAT3 in bladder cancer tissues as prospective for target therapy." (PMID 32102537, 2020). "Activation of JAK-STAT signalling, mostly by phosphorylation and protein level of STAT3/5 has been described in bladder cancer by several groups." (PMID 32046095, 2020). "C-Jun has been previously shown to interact with STAT3 and co-operatively regulate the transcription of their target genes in bladder cancer." (PMID 31918717, 2020).
bladder cancer (continued). "Low GATA3 levels have been reported to regulate self-renewal and tumorigenicity in bladder cancer stem cells by modulating STAT3 expression." (PMID 33408272, 2020). "The knockdown of EIF5A2 in bladder cancer suggests that by increasing the enrichment of STAT3, EIF5A2 elevated TGF TGFβ1 expression by inducing EMT." (PMID 32605067, 2020). "Based on the TCGA results, we decided to analyse expression and activation level of JAK1/2 and STAT3 in a panel of 10 different bladder cancer derived cell lines." (PMID 32046095, 2020). "Increased protein level and constitutive activation of STAT3 have also been reported in bladder cancer." (PMID 32046095, 2020). "ARRB2 depletion in bladder cancer cells was shown to induce phosphorylation/activation of STAT3, whereas overexpression of ARRB2 had the opposite effect." (PMID 33297302, 2020). "High STAT3 expression was detected in 51.3% from 149 patient specimens with invasive bladder cancer by immunohistochemistry." (PMID 32046095, 2020). "Our results provide evidence that inhibitors against STAT3/5 are promising as novel mono- and combination therapy in bladder cancer." (PMID 32046095, 2020). "Both treatment conditions enhanced phospho-tyrosine Stat3 level in the T24 bladder cancer and the human PDX model, which was significantly diminished by a CD167a/DDR1 selective kinase inhibitor (DDR1-IN-1)." (PMID 31086186, 2019). "miR-153 targeted IDO1 expression and inhibited bladder cancer cell tryptophan metabolism through inactivating the IL6/STAT3/VEGF signaling pathway." (PMID 31355138, 2019). "Collectively, these results uncovered CD167a-HSP90 as a newly-identified interacting protein complex, which connected Stat3 as a downstream molecule to the CD167a canonical axis in bladder cancer." (PMID 31086186, 2019). "Here, the authors show that airway smooth muscle cells are a collagen III rich niche bladder cancer cells expressing CD167a, and Stat3 is a downstream target for abrogating these collagen III/CD167a-driven metastatic foci." (PMID 31086186, 2019). "At the gene level, miR-153 targeted IDO1 expression and inhibited bladder cancer cell tryptophan metabolism through inhibiting IL6/STAT3/VEGF signaling." (PMID 31355138, 2019). "In the current study, we found that miR-153 expression reduced IL6 secretion in bladder cancer cells, thereby inhibiting STAT3 signaling and VEGF expression." (PMID 31355138, 2019). "Geldanamycin effectively disrupted the interaction of HSP90 with CD167a in the T24 model, and convincingly diminished ASMC-induced Stat3 tyrosine phosphorylation in a dose-dependent manner, both in T24 bladder cancer and the human PDX models." (PMID 31086186, 2019). "For example, in a syngeneic bladder cancer mouse model, NK depletion abrogates the effects of a STAT3 inhibitor on tumor rejection." (PMID 31609088, 2019). "IL-6 is the most well-known traditional activator of STAT3, and positive staining of IL-6 in bladder cancer was reported to be significantly correlated with higher clinical stage and higher recurrence rate." (PMID 30091994, 2018). "In summary, we demonstrated the decreased PKM2 enhanced the efficiency of THP on bladder cancer via inhibiting STAT3 and activating AMPK." (PMID 29512924, 2018). "On a final note, there is one additional aspect of Blcap biology that should be looked into in relation to Stat3 signaling, namely that Blcap undergoes multiple A-to-I editing events in bladder cancer." (PMID 29190807, 2017). "Previous studies have also found that between 19 and 40% of bladder cancers have elevated expression of p-Stat3, a figure comparable to the one we found (20%) for Blcap overexpression in bladder cancer." (PMID 29190807, 2017). "Our findings propose Blcap as a novel interactor of Stat3 in bladder cancer and, possibly, as a factor involved in bladder cancer progression through the Stat3 signaling pathway." (PMID 29190807, 2017).
bladder cancer (continued). "In this research, we demonstrated that metformin is capable of repressing bladder cancer CSC repopulation through inhibiting the COX2/PGE2/STAT3 axis in both animal and cellular models." (PMID 27058422, 2016). "Immunohistochemistry shows the levels of p-STAT3 in the bladder cancer animal model treated with metformin are consistently lower." (PMID 27058422, 2016). "In conclusion, to our best knowledge that we are the first to use both cell and animal models to systemically demonstrate that metformin inhibits bladder cancer progression by inhibiting cancer stem cell repopulation through the COX2/PGE2/STAT3 axis." (PMID 27058422, 2016). "In conclusion, we are the first to systemically demonstrate in both animal and cell models that metformin inhibits bladder cancer progression by inhibiting stem cell repopulation through the COX2/PGE2/STAT3 axis." (PMID 27058422, 2016). "Since STAT3, a downstream target of COX2/PGE2, is involved in the regulation of primitive CK14+ cell expansion, we propose that in bladder cancer metformin inhibits CK14+ cell repopulation through the COX2/PGE2/STAT3 axis." (PMID 27058422, 2016). "Based on these findings, we proposed that metformin suppressed bladder cancer development by inhibiting cancer stem cell repopulation via the COX2/PGE2/STAT3 axis." (PMID 27058422, 2016). "The purpose of this study is to evaluate the effects of metformin on bladder cancer using an in vitro model of human urinary bladder-cancer and an in vivo model of rat orthotopic bladder cancer and explore the role of metformin in regulating STAT3 pathway." (PMID 26245871, 2015). "It is reported that STAT3 are frequently activated in various cancer types, including bladder cancer." (PMID 25849286, 2015). "By using phosphorylation level of STAT3 at Y705 as a surrogate marker, Lin and colleagues found that STAT3 is overactivated in 19% human bladder cancer tissues (n = 100)." (PMID 25849286, 2015). "We found that δ-T3 suppressed the phosphorylation level of STAT3(Y705) in a concentration-dependent manner in both of T24 and 5637 bladder cancer cell lines." (PMID 25849286, 2015). "It has been reported that STAT3 activation in urothelial basal cells results in progression of CIS to invasive cancer in an orthotopic mouse bladder cancer model." (PMID 26245871, 2015). "Next we constructed the STAT3-KNOCKDOWN T24 cell line (T24/STAT3-KD) and the normal control cell line (T24/control) to compare the metformin sensitivity between STAT3 inactivated and activated bladder cancer cells." (PMID 26245871, 2015). "When STAT3 pathway was inactivated in T24/STAT3-KD cells, these bladder cancer cells, like T24 cells treated with metformin, turned to the phenotypes of weakened prolifearation, migration and invasion abilities." (PMID 26245871, 2015). "In an orthotopic mouse bladder cancer model, STAT3-transgenic mice, compared with the wild-type counterparts, developed invasive cancer directly from carcinoma in situ (CIS) in a shorter time, bypassing the noninvasive papillary tumor stage." (PMID 26245871, 2015). "Taken together, our data demonstrated that δ-T3 treatment decreased the phosphorylation level along with the nuclear translocation of STAT3 protein, resulting in the transcriptional reduction of its downstream target genes in human bladder cancer cells." (PMID 25849286, 2015). "As a classical activator of TLR4, the lipopolysaccharide (LPS) can remarkably increase the level of phosphorylated STAT3 in the human bladder cancer T24 cell line, suggesting the activation of STAT3 by TLR4 signaling." (PMID 26631279, 2015). "Recent study further revealed that constitutively activated STAT3 in urothelial cells accelerates the progression into muscle-invasive bladder cancer, indicating that STAT3 plays a critical role in bladder cancer development." (PMID 25849286, 2015).
bladder cancer (continued). "In vitro experiments revealed that the metformin could efficiently inhibit STAT3 activation, which was associated with the cell cycle arrest, reduction of cell proliferation, migration and invasiveness, and increase in apoptotic cell death of bladder cancer cell lines." (PMID 26245871, 2015). "High protein levels of phosphorylated STAT3 were only observed in tumor tissues and also in six different bladder cancer cell lines, indicating pronounced STAT3 activation." (PMID 25268165, 2014). "We have also identified the activation of ERK1/2, p38MAPK, JNK, JAK1, JAK2, JAK3, Stat1, Stat2, and Stat3 in bladder cancer cells." (PMID 22962576, 2012). "Binding of IL-28A to IL-28AR1 induced the activation of ERK1/2, p38MAPK, and Jak/Stat (Jak2, Jak3, Stat1, Stat3, and Stat5) signaling pathways in bladder cancer cells." (PMID 22962576, 2012). "Our previous study indicates that nicotine induced bladder cancer cell proliferation through Stat3 and ERK1/2 signalings instead of via AKT pathway." (PMID 21559255, 2011). "We found that down-regulation of ETK in bladder cancer cells attenuated STAT3 and AKT activity whereas exogenous overexpression of ETK had opposite effects." (PMID 21408190, 2011). "Knockdown ETK leads to diminished activation of STAT3, which plays a role in bladder cancer invasion, partially explained the possible mechanism of invasion inhibition." (PMID 21408190, 2011). "Western blot analysis showed that elevated p-Stat3 was also found in bladder cancer cell lines, UMUC-3, 253J and WH." (PMID 18939995, 2008). "We found that elevated Stat3 phosphorylation in 19 of 100 (19%) bladder cancer tissues as well as bladder cancer cell lines, WH, UMUC-3 and 253J." (PMID 18939995, 2008). "This indicated that STA-21 inhibition is specific to bladder cancer cells that have constitutive activation of Stat3." (PMID 18939995, 2008). "Overactive FGFR3 and ERBB2 in bladder cancer presumably would activate Stat3 that is down-stream to these two receptor tyrosine kinases." (PMID 18939995, 2008). "Tissue microarray immunohistochemistry indicated that Stat3 phosphorylation was elevated in bladder cancer tissues." (PMID 18939995, 2008). "Among 100 primary bladder cancer biopsy tissues, 19% appears positive in p-Stat3 immunostaining in nuclei, cytoplasm or both compartments." (PMID 18939995, 2008). "Total Stat3 expressions correspondingly reflected the dose-dependent increase of dnStat3 expressions in these bladder cancer cells." (PMID 18939995, 2008). "Interruption of Stat3 pathway using a dnStat3 or STA-21 affects bladder cancer cell growth and induces the activation of apoptotic caspases." (PMID 18939995, 2008). "We also examined the expression of anti-apoptotic genes and cyclin D1 in WH bladder cancer cells when Stat3 pathway was targeted by rAd/dnStat3 or STA-21." (PMID 18939995, 2008). "One way to investigate the functions of activation of Stat3 in bladder cancer is to interrupt Stat3 signaling pathway in bladder cancer cell lines with elevated p-Stat3." (PMID 18939995, 2008). "We found that 19 of 100 (19%) bladder cancer biopsy tissues had elevated expression of phosphorylated-Stat3 (p-Stat3) using an immunohistochemical staining with a p-Stat3 specific monoclonal antibody." (PMID 18939995, 2008). "Three representative bladder cancer tissues with p-Stat3 positive immunostaining (scale 2–3) are shown, whereas normal bladder tissues were negative or very weak (scale 0–1) with immunostaining." (PMID 18939995, 2008). "The elevated p-Stat3 in the bladder cancer tissues was scored and summarized according to immunostaining intensities." (PMID 18939995, 2008). "It has been indicated that G-CSF potently activates STAT3 and STAT3-dependent survivin expression in bladder cancer cells." (PMID 18021394, 2007).